RNU6-169P (RNA, U6 small nuclear 169, pseudogene)
Gene: Small nuclear RNA gene on chromosome 2 (195,514,036 to 195,514,142, forward strand). Ensembl gene ENSG00000202206.
Homologues: Orthologues: chimpanzee U6 (99% identical), mouse Gm24851 (76% identical). Paralogues in human: RNU6-17P (88% identical), RNU6-18P (88% identical), RNU6-737P (88% identical), RNU6-1 (87% identical), RNU6-12P (87% identical), RNU6-13P (87% identical), RNU6-16P (87% identical), RNU6-2 (87% identical), RNU6-32P (87% identical), RNU6-3P (87% identical), RNU6-4P (87% identical), RNU6-5P (87% identical), and 1289 more.